DNMT1 (DNA methyltransferase 1)
Diseases named in the same sentence as DNMT1 in open-access papers (continued):
Sharing a sentence is not in itself a finding about the gene and the disease.
glioblastoma (continued). "We show that DNMT1 expression is lower in mesenchymal glioblastoma compared to proneural tumors." (PMID 28036297, 2017). "The low expression of IGFBP2 observed in some glioblastoma cell lines, is associated with methylation of the IGFBP2 promoter and can be restored with 5-azacytadine treatment suggesting regulation by DNA methyltransferase 1 (DNMT1)." (PMID 25774149, 2015). "Moreover, since DNMT gene promoters contain CpG islands, it is plausible that these enzymes could self-regulate via promoter methylation in CC, as observed in the aberrant methylation of the DNMT1 promoter in glioblastoma." (PMID 41226543, 2025). "miR‐148‐3p is primarily involved in glioblastoma multiforme (GBM) through its direct regulatory effects on DNMT1 and recombinant human runt‐related transcription factor 3 (RUNX3)." (PMID 40387409, 2025). "Our findings show that dual DNMT1 and HDAC inhibition in two glioblastoma cell lines led to a hundreds-fold increase in the expression of the GTA-p63 mRNA variant, while TA-p63 was induced at a comparatively much lower level." (PMID 40498028, 2025). "Overall, our findings reveal that DNA methyltransferases (DNMT1 and DNMT3A) mediate the hypermethylation of the CBX7 promoter, leading to its frequent downregulation in glioblastoma tissues and cell lines." (PMID 39988672, 2025). "A previous study showed that Dnmt1, Dnmt3a, and Dnmt3b can regulate the methylation status of BIRC5 in glioblastoma multiforme." (PMID 35664300, 2022). "In contrast, aberrant expression of DNMTs, for example, high expression of DNMT1 and DNMT3B and low expression of DNMT3A, has been reported in glioblastoma." (PMID 34214250, 2022). "Taken together, this data suggests that DNMT1 and HDACs sequential inhibition can affect the cell growth and viability in different glioblastoma cell models, and that DAC, but not SB939, contributed the most to this effect." (PMID 40498028, 2025). "In glioblastoma, lncRNA AGAP2-AS1 recruits lysine-specific histone demethylase 1 (LSD1) and enhancer of zeste homolog 2 (EZH2) to the TFPI2 promoter, leading to H3K27me3 and DNMT1-mediated methylation, silencing TFPI2 and promoting tumor progression." (PMID 40361374, 2025). "Additionally, our study revealed that DNMT1 and DNMT3A mediate the hypermethylation of the CBX7 promoter, leading to its frequent silencing in glioblastoma cell lines and primary tumor tissues." (PMID 39988672, 2025). "Thus, the combined inhibition of DNMT1 and HDAC was able to slightly induce apoptosis in these glioblastoma cell models." (PMID 40498028, 2025). "Alternatively, H3K9 trimethylation may be mediated by DNA methyltransferases of which DNMT1 and DNMT3 are known to be deregulated in glioblastoma." (PMID 25602259, 2015). "We investigated neuroblastoma and glioblastoma cell lines with mature CIK cells and the PPARγ antagonist GW‐9662 to assess the effects on cell viability, candidate gene expression (Wnt/β‐catenin signalling, DNMT1) and global methylation levels (5‐methylcytosine, LINE‐1)." (PMID 39679632, 2024). "Moreover, increased expression of DNMT1 and DNMT3B was recently described in glioblastoma." (PMID 28036297, 2017).
bladder cancer (47 papers, 2011 to 2026). "Our study results showed a significant association between the rs2228611 of the DNMT1 gene and the occurrence of bladder cancer in the study population under the genetic models: Codominant model AG vs. GG and Dominant model AA+AG vs. GG." (PMID 38504781, 2024). "According to our research, the present study is the first reviewed study to assess the association between the rs2228611 polymorphism of the DNMT1 gene and bladder cancer risk in the Algerian population and worldwide." (PMID 38504781, 2024). "The aim of this study was to examine the role of miRNAs regulation by DNMT1 and its underlying mechanisms in bladder cancer." (PMID 26090723, 2015). "We found that the miR-424, -145 and -202 levels were obviously increased in association with decreased miR-223 and -98 levels in bladder cancer cells with the DNMT1-silencing vector compared with those with control vectors in vitro." (PMID 26090723, 2015). "We previously reported that higher DNMT1 levels were associated with aggressive tumor behavior and higher clinical stage in bladder cancers." (PMID 24886404, 2014). "Based on the bioinformatics studies cited above, we suggest that the rs2228611 may lead to dysfunction of the DNMT1 enzyme, which can lead to hypomethylation of bladder cancer cell DNA because of its deficient activity." (PMID 38504781, 2024). "A statistically significant association was found between the rs2228611 of the DNMT1 gene and the occurrence of bladder cancer under the genetic models: codominant AG vs. GG (OR=2.54; 95% CI= 1.21-5.51, adj p=0.015,) and dominant AA+AG vs. GG (OR=2.24; 95% CI=1.12-4.60, adj p=0.023)." (PMID 38504781, 2024). "In this study, we aimed to evaluate the effect of the polymorphisms rs2228611 of the DNMT1 gene and rs1569686 of the DNMT3B gene on the susceptibility to develop Bladder Cancer in the Algerian population." (PMID 38504781, 2024). "Knockdown of PTEN mitigated DNMT1’s effects on bladder cancer cell proliferation and migration, indicating that miR-152-3p inhibits DNMT1 expression, which in turn affects PTEN via DNA methylation regulation." (PMID 39606232, 2024). "Here, the authors showed that silencing DNMT1 inhibited the growth and migration of tumour cells, whereas increasing DNMT1 expression had the opposite effect, confirming its role in bladder cancer." (PMID 36980741, 2023). "HGC-27 and MGC-803 cell lines were transfected with the miR-448 mimic and NC and subjected to DNMT1 overexpression to determine the effect of miR-448/DNMT1 on adjusting SEPT9 methylation in bladder cancer cells." (PMID 35528235, 2022). "Upregulation of miR-448 promotes SEP9 protein expression and inhibits the growth, metastasis, and spread of bladder cancer cells, and these processes are reversed by the overexpression of DNMT1." (PMID 35528235, 2022). "As an example, DBCCR1-003 lncRNA binds to DNMT1 and blocks the methylation of DBCCR1 by DNMT1 in bladder cancer cells." (PMID 37533667, 2022). "Previous study revealed that silencing of miR-152 contributed to DNMT1-mediated CpG methylation of the PTEN promoter in bladder cancer." (PMID 36276278, 2022). "We demonstrated novel regulatory circuits involving miR-148a-3p/ERBB3/AKT2/c-myc and DNMT1 that controlled bladder cancer progression." (PMID 27906180, 2016). "We confirmed that DNMT1 was a direct miR-148a-3p target and that miR-148a-3p expression significantly negatively correlated with DNMT1 expression in bladder cancer tissues (r=0.108, P=0.041)." (PMID 27906180, 2016). "Together, these results indicate that DNMT1 and miR-148a-3p establish a positive feedback loop that is disrupted in both bladder cancer cells and bladder cancer tissues." (PMID 27906180, 2016). "It is possible that upregulated DNMT1 leads to hypermethylation of CpG islands in the promoter regions of many genes in bladder cancer cells." (PMID 27499248, 2016).
bladder cancer (continued). "In the present study, we sought to evaluate the potential role of miRNAs regulated by DNMT1 and the mechanisms responsible for their action in bladder cancer." (PMID 26090723, 2015). "We also evaluated the predictive power of the target miRNA and its link to DNMT1 from 124 clinical bladder cancer specimens." (PMID 26090723, 2015). "Our results revealed that the miR-424 level is significantly increased when blocking DNMT1 in bladder cancer cells." (PMID 26090723, 2015). "We outlined the main signaling pathways that are thought to link DNMT1 and miR-424 to bladder cancer." (PMID 26090723, 2015). "Here we demonstrated that miR-424 was transcriptionally regulated by DNMT1 activity in bladder cancer cells." (PMID 26090723, 2015). "The predictive powers of miRNA 424 and DNMT1 were further examined in terms of the clinical outcomes of bladder cancer." (PMID 26090723, 2015). "Accordingly, we suggested that DNMT1 activity is critical for the downregulation of miR-424 expression in bladder cancer." (PMID 26090723, 2015). "To explore this possibility, we used a microRNA Taqman array to analyze the role of DNMT1 in the expression of miRNA in bladder cancer." (PMID 26090723, 2015). "Accordingly, we suggested that the downregulation of miR-424 mediates the activation of EGFR signaling in DNMT1-positive bladder cancer." (PMID 26090723, 2015). "The level of miR-424 was more significantly increased in bladder cancer cells with DNMT1-silencing vectors, compared to the others." (PMID 26090723, 2015). "Our previous data indicated that the EGFR-AKT pathway mediated the aggressive tumor behavior in DNMT1-positive bladder cancer." (PMID 26090723, 2015). "DNMT1 was reported to be over-expressed in several tumor types, and play an important role in the prognosis of bladder cancer." (PMID 26090723, 2015). "We found there was a significant correlation between positive staining for IL-6 and DNMT1 on IHC staining of bladder cancer specimens." (PMID 23637926, 2013). "Higher DNMT1 levels were associated with aggressive tumor behavior and EMT changes in bladder cancers." (PMID 23637926, 2013). "In human bladder cancer cells, selective depletion of DNMT1 with siRNA induced demethylation and reactivation of the silenced tumor-suppressor gene CDKN2A." (PMID 21999220, 2011). "The miR-152-3p/DNMT1/PTEN pathway plays a crucial role in bladder cancer development." (PMID 39606232, 2024). "Diabetic LEC treated with 5 μmol/l zebularine showed substantially decreased 5-methylcytosine and significantly (40.9%) reduced DNMT1 levels (p<0.05), like the DNMT1 depletion reported previously for human bladder cancer cells, indicating effective DNA demethylation." (PMID 37460827, 2023). "Taken together, our study demonstrates novel regulatory circuits involving miR-148a-3p/ERBB3/AKT2/c-myc and DNMT1 that controls bladder cancer progression, which may be useful in the development of more effective therapies against bladder cancer." (PMID 27906180, 2016). "We found that T24 bladder cancer cells express two-fold higher levels of DNMT1 than normal cells." (PMID 27499248, 2016). "Here, we also found that IL-6 and DNMT1 expression were correlated in bladder cancer." (PMID 27499248, 2016). "Furthermore, we identified novel regulatory circuits involving miR-148a-3p/ERBB3/AKT2/c-myc and DNA methyltransferase 1 (DNMT1) in the control of bladder cancer progression." (PMID 27906180, 2016). "Our study identified regulatory loops between miR-148a-3p/ERBB3/AKT2/c-myc and DNMT1 in bladder cancer regulation, which could prove useful in the development of effective and therapies against bladder cancer." (PMID 27906180, 2016). "We previously reported that the EGFR-PI3K-AKT pathway may be the mechanism responsible for the aggressive tumor behavior in DNMT1-positive bladder cancer." (PMID 26090723, 2015). "Therefore, the link between DNMT1 and the expression of miRNAs in bladder cancer was evaluated in the present study." (PMID 26090723, 2015).
bladder cancer (continued). "We postulated that alterations in miRNA expression could represent a mechanism responsible for the role of DNMT1 in bladder cancer." (PMID 26090723, 2015). "In addition, the link between TM signaling, the activation of NF-κB and DNMT1 in bladder cancer was demonstrated." (PMID 24886404, 2014). "We therefore suggest that inhibition of TM expression might be responsible for aggressive tumors in DNMT1-positive bladder cancer." (PMID 24886404, 2014). "The relationship between IL-6/STAT3 signaling and DNMT1 in bladder cancer was further examined to see whether regulation of IL-6/STAT3 signaling results in changes of DNMT1 expression." (PMID 23637926, 2013). "Although the mechanism responsible for increased expression of DNMT1 in UC is not well known, a previous report of DNMT1 protein overexpression in bladder cancer suggested that the mRNA expressions of DNMT1 we observed in UC may be attributable to increased cell proliferation caused by inflammation." (PMID 26862732, 2016). "Accordingly, DNMT1 may play a role in the regulation of miR-424 expression in bladder cancer." (PMID 26090723, 2015). "Thus, alterations in miRNAs expression may represent a mechanism responsible for the role of DNMT1 in bladder cancer." (PMID 26090723, 2015). "Moreover, TM is a clinically significant predictor that might be partially responsible for aggressive tumors in DNMT1-positive bladder cancer." (PMID 24886404, 2014). "Therefore, it is suggested that activation of AKT might be responsible to the increased DNMT1 in IL-6-positive bladder cancers." (PMID 23637926, 2013). "We previously reported that DNMT1 could be a significant clinical predictor of bladder cancer." (PMID 23637926, 2013). "In the present study, we aim to evaluate possible implication of SNPs of the DNA methylation genes DNMT1 and DNMT3B in the occurrence of bladder cancer in the Algerian population." (PMID 38504781, 2024). "In bladder cancer, lncRNA DBCCR1-003 also binds to DNMT1, inducing hypermethylation on the promoter region of DBCCR1." (PMID 33050646, 2020). "DNA methyltransferase 1 (DNMT1) and miR-148a-3p function in a positive feedback loop in bladder cancer." (PMID 27906180, 2016). "Furthermore, DNMT1 was identified as a potential target of miR-152, with luciferase reporter gene assays showing direct binding of miR-152 to DNMT1 3′UTR, leading to its inhibition in bladder cancer cells." (PMID 39606232, 2024). "Studies investigating the association between polymorphism rs2228611 of the DNMT1 gene and rs1569686 of the DNMT3B gene and bladder cancer are rare almost none." (PMID 38504781, 2024). "DNMT1 was over-expressed, whereas DNMT3B was downregulated in bladder cancer cells." (PMID 36077697, 2022). "DBCCR1-003/DNMT1 complex reduces the expression of DBCCR1 and apoptosis of bladder cancer." (PMID 33050646, 2020). "In our investigation we also reported that the RRx-001 agent, by downregulating the DNA-methyltransferase 1 (DNMT1) protein, generated in bladder cancer cells an immunomodulatory activity by inducing an interferon response through epigenetic induction of viral mimicry." (PMID 30786932, 2019). "Mechanistically, although HNF1A-AS1 had been reported to mediate the binding of DNMT1 to E-cadherin in lung adenocarcinoma, we did not found HNF1A-AS1 interact with DNMT1 and E-cadherin in bladder cancer." (PMID 29100339, 2017). "Immunohistochemistry (IHC) analysis indicated that DNMT1 expression was significantly higher in bladder cancer tissues compared with adjacent non-tumor tissues (P<0.001) and that DNMT1 localized to the nucleus." (PMID 27906180, 2016). "We further compared the expression of miR-148a-3p, DNMT1 and ERBB3 in bladder cancer tissues." (PMID 27906180, 2016). "Next, we performed real-time RT-PCR to quantify the expression levels of miR-424, 98, 145, 223 and 202 in bladder cancers with or without DNMT1 inhibition." (PMID 26090723, 2015).
bladder cancer (continued). "There was a negative correlation between the expression of TM and DNMT1 in bladder cancer specimens." (PMID 24886404, 2014). "Furthermore, the analysis of clinical specimens from bladder TCC patients showed that 53 (43%) had positive miR-424 immunoreactivity in bladder cancer tissues and there was a negative correlation between the expression levels of miR-424 and DNMT1." (PMID 26090723, 2015). "Additionally, the IHC analysis indicated positive staining for DNMT1 in 46% of the bladder cancer tissues, and there was a negative correlation between the expression levels of miR-424 and DNMT1." (PMID 26090723, 2015). "Finally, in a multivariate Cox model including age, gender, tumor grade, lymph node invasion, ERBB3 expression, DNMT1 expression and miR-148a-3p expression, we found that ERBB3 overexpression was a poor independent prognostic factor for the overall survival in patients with bladder cancer (P=0.044)." (PMID 27906180, 2016).
Obesity (45 papers, 2015 to 2026). Accumulation of substantial excess body fat. "Primarily differentiated adipocytes from Dnmt1-deficient or fl/fl mice were treated with saturated fatty acids and proinflammatory cytokines, two obesity-associated factors whose levels are commonly elevated in obesity." (PMID 40666843, 2025). "Obesity triggers the release of pro-inflammatory cytokines, which in turn can facilitate the elevation of DNA methyltransferase 1 (DNMT1) expression and its associated enzymatic activity." (PMID 38068717, 2023). "On the other hand, the association of Dnmt1 polymorphism with obesity has also been reported in human population." (PMID 34824202, 2021). "While the rise in wound healing may be attributed to systemic causes because of increased insulin sensitivity and obesity, DNMT1 targeting was recognised as a viable treatment technique in diabetic macrophages and needs more investigation." (PMID 36831151, 2023). "Thus, our data consistently indicate that DNMT1 deficiency in brown fat promotes obesity and impairs insulin sensitivity in mice." (PMID 34824202, 2021). "In consistence with our prior findings on Dnmt1 or 3a, deletion of Dnmt3b at early stage of brown fat development using Myf5-Cre also promoted diet-induced obesity and insulin resistance, which was associated with the induction of myogenic program in brown fat." (PMID 34439754, 2021). "A recent study demonstrated that Dnmt1 may contribute to obesity-associated inflammation and insulin resistance by promoting hypermethylation at the Adipoq locus." (PMID 29091029, 2017). "Thus, it is possible that the UTX/DNMT1 pathway may also regulate obesity and associated metabolic diseases in humans." (PMID 34824202, 2021). "It has been reported that pharmacological inhibition of PPARγ1 promoter DNA methylation via 5-aza-2′-deoxycytidine or genetically by DNMT1 knockout promotes macrophage alternative activation in obesity." (PMID 40166716, 2025). "Conversely, inflammatory factors promote DNMT1 activity in adults with obesity, thus suggesting a bidirectional interaction between DNMT enzymatic activity and the inflammatory response in the obese microenvironment." (PMID 40620794, 2025). "T2D mouse models of genetic (db/db) along with diet-mediated obesity (DIO) have been reported to display increased DNMT1 in BMDMs and to promote a pro-inflammatory macrophage phenotype." (PMID 36831151, 2023). "Similar implementation of DNMT1 in IR pathogenesis has been observed by others, where an increased expression of DNMT1 correlated with obesity and IR." (PMID 34207541, 2021). "To determine the role of brown adipocyte DNMT1 in diet-induced obesity, we challenged male and female D1KO mice and their littermate control fl/fl mice with HFD for up to 24 weeks." (PMID 34824202, 2021). "In a mouse model of obesity, dietary supplementations of saturated fatty acids significantly increased DNMT1 expression and macrophages and increased methylation of the promoter region of PPAR-γ." (PMID 32309269, 2020). "Placental mRNA abundance for the folate receptor alpha (FOLR1) was reduced with obesity, whilst DNMT1 was increased with raised BMI, responses that were unaffected by GD." (PMID 30428605, 2018). "In fact, fatty acid binding protein 4 (FABP4)/IL-6/STAT3/DNA methyltransferase 1 (DNMT1) have been shown to link obesity to the growth of AML cells." (PMID 29269861, 2017). "To confirm further the proinflammatory role of DNMT1 in macrophages, we isolated the PMs from wild-type or TgDNMT1 mice and challenged them with the atherogenic metabolite ox-LDL6 or the obesity-associated factor, LPS." (PMID 27530451, 2016). "In adipocytes, DNA methylation at the particular region of adiponectin promoter, the R2, is mediated by DNMT1, and induces the subsequent formation of heterochromatin structure to suppress adiponectin gene expression in obesity." (PMID 26139044, 2015).